F3 (coagulation factor III, tissue factor)
Description:
Initiates blood coagulation by forming a complex with circulating factor VII or VIIa. The [TF:VIIa] complex activates factors IX or X by specific limited proteolysis. TF plays a role in normal hemostasis by initiating the cell-surface assembly and propagation of the coagulation protease cascade.
Synonyms: TF; CD142; TFA
Tractability: Small molecule: a structure with a bound ligand is known; a high-quality ligand is known; it belongs to a druggable protein family. Antibody: UniProt places it where antibodies can reach, with high confidence; its Gene Ontology location is reachable by antibodies, with high confidence; UniProt predicts a signal peptide or a membrane-spanning region. PROTAC: ubiquitination databases record sites on it; a small molecule that binds it is known. Other modalities: an approved drug acts on it.
Target class: Surface antigen
Chemical probes: P-Cinnamoylphenol, PD081388, PD083064, curcumin, oleanolic acid (high quality)
Gene: Protein-coding gene on chromosome 1 (94,529,173 to 94,541,851, reverse strand). Ensembl gene ENSG00000117525.
Subcellular location: Membrane (Isoform 1); Secreted (Isoform 2)
Subcellular location (Human Protein Atlas): Vesicles; Predicted to be secreted
Pathways (Reactome):
Hemostasis: Initiation of coagulation cascade; Regulation of clotting cascade
Signal Transduction: NGF-stimulated transcription
Gene Ontology:
Molecular function: phospholipid binding; protease binding; protein binding; serine-type endopeptidase activity; cytokine receptor activity
Biological process: activation of blood coagulation via clotting cascade; activation of plasma proteins involved in acute inflammatory response; blood coagulation; positive regulation of angiogenesis; positive regulation of endothelial cell apoptotic process; positive regulation of endothelial cell proliferation; positive regulation of gene expression; positive regulation of interleukin-8 production; positive regulation of platelet-derived growth factor receptor signaling pathway; positive regulation of positive chemotaxis; positive regulation of TOR signaling; protein processing; cytokine-mediated signaling pathway; positive regulation of cell migration; response to stress
Cellular component: cell surface; external side of plasma membrane; extracellular matrix; extracellular region; membrane; serine-type peptidase complex; plasma membrane
Genetic constraint (gnomAD): Loss-of-function variants: 17 observed, 30.38 expected, observed/expected ratio (o/e) 0.56, 90% interval 0.38 to 0.84. The upper end of that interval is the gene's LOEUF score, 0.84, which puts it in group 3 of 6, group 1 being the genes least tolerant of losing a copy. Missense variants: 339 observed, 344.66 expected, observed/expected ratio (o/e) 0.98, 90% interval 0.9 to 1.08. Synonymous variants: 145 observed, 136.3 expected, observed/expected ratio (o/e) 1.06, 90% interval 0.93 to 1.22.
Homologues: Orthologues: chimpanzee F3 (98% identical), macaque F3 (95% identical), pig F3 (71% identical), rabbit F3 (69% identical), dog F3 (65% identical), guinea pig F3 (64% identical), rat F3 (54% identical), mouse F3 (53% identical), tropical clawed frog f3 (31% identical), zebrafish f3a (31% identical). Paralogues in human: IL20RA (20% identical), IFNAR2 (19% identical), IL22RA2 (18% identical), IFNGR1 (17% identical), IL20RB (17% identical), IFNGR2 (16% identical), IL10RB (16% identical), IL22RA1 (16% identical), IFNLR1 (15% identical), IL10RA (15% identical), IFNAR1 (13% identical).
Diseases named in the same sentence as F3 in open-access papers:
F3 is named in the same sentence as 195 diseases in open-access papers, as found by Europe PMC text mining. Sharing a sentence is not in itself a finding about the gene and the disease. The quoted sentences say what the papers report.
thrombosis (50 papers, 2013 to 2025). "The F3 gene, also known as CD142, is commonly associated with thrombosis and vascular endothelial function and is a potential risk factor for CHD." (PMID 39868675, 2025).
Sepsis (43 papers, 2006 to 2026). Sepsis is defined as life-threatening organ dysfunction caused by a dysregulated host response to infection. "STING-dependent signalling drove lethal coagulation in murine sepsis through the release of coagulation factor III (F3), a key initiator of blood coagulation, further widening the scope of functional outcomes of caspase activation following severe bacterial infections." (PMID 35712726, 2022).
hypercoagulability (33 papers, 2011 to 2026). "Tissue factor (F3) is a critical initiator of extrinsic coagulation pathway and is associated with hypercoagulation in various diseases." (PMID 36400883, 2022).
glioma (12 papers, 2000 to 2025). A benign or malignant brain and spinal cord tumor that arises from glial cells (astrocytes, oligodendrocytes, ependymal cells). "One membrane-bound protein that is highly expressed in a subset of gliomas is Tissue Factor (TF), which is encoded by the gene F3." (PMID 40075681, 2025). "We previously showed that gliomas with mutations in isocitrate dehydrogenase 1 and 2 (IDHmut) methylate and suppress F3, the gene encoding Tissue Factor (TF), and that this contributes to the reduced aggressiveness of IDHmut gliomas compared to high TF-expressing GBM." (PMID 40075681, 2025).
melanoma (10 papers, 2012 to 2024). A malignant, usually aggressive tumor composed of atypical, neoplastic melanocytes. "We also found that although some established YAP/TAZ target genes (CRIM1, F3, ANKRD1) correlated strongly with CTGF and CYR61 expression in human melanoma, others did not (WWC1, FOSL1, FSTL3)." (PMID 38473214, 2024).
lung cancer (7 papers, 2017 to 2024). A malignant neoplasm involving the lung. "Using Kaplan-Meier clinical databases we found that tissue factor (TF/F3) is highly expressed in liver and lung carcinoma, which indicates TF can be a good target molecule for the liver and lung cancer treatment." (PMID 34109110, 2021).
malaria (4 papers, 2012 to 2025). Malaria is a serious and sometimes fatal disease caused by a parasite that commonly infects a certain type of mosquito which feeds on humans. "Similar to the evidence from IP mice, malaria-exposed SM9-1 trophoblast displayed the ability to support coagulation by marked increases of F3 transcription, which steadily increased, peaking at 8 hours post-iRBC exposure with a mean fold increase of 2.5±0.1." (PMID 22347435, 2012).
myeloid leukemia (2 papers, 2006 to 2017). A clonal proliferation of myeloid cells and their precursors in the bone marrow, peripheral blood, and spleen. "Our analysis suggests that a direct link from NFKB1 to F3 (coagulation factor III/Tissue factor) is among the top links that discriminate between the two types of myeloid leukemia." (PMID 16670008, 2006).
renal fibrosis (2 papers, 2024 to 2025). A final common manifestation of a wide variety of chronic kidney diseases characterized by glomerulosclerosis and tubulointerstitial fibrosis. "In addition, the expression of genes associated with complement and coagulation activation, such as F3, Fga, Pai1, C3, and C5ar1, was also elevated in the two different renal fibrosis models, indicating the upregulation of local renal coagulation and complement cascades in the pathogenesis of CKD." (PMID 41324413, 2025).
Anxiety (1 paper, 2016). Intense feelings of nervousness, tension, or panic often arise in response to interpersonal stresses. "Psychological distress measured by anxiety, depression and hostility was positively associated, and happiness and life satisfaction were inversely associated with average Intercellular Adhesion Molecule-1 (ICAM-1) and coagulation factor III (F3) promoter methylation levels." (PMID 26733571, 2016).
hemosiderosis (1 paper, 2022). Accumulation of iron in internal organs. "Notably, cardiac-specific f3 knockout mice demonstrate a mild hemostatic defect but significant fibrosis and hemosiderosis when chemically challenged with isoproterenol, and humanized low-TF mice similarly show significant cardiac fibrosis and left ventricular dysfunction in adulthood." (PMID 36449521, 2022).
leiomyoma (1 paper, 2023). A well-circumscribed benign smooth muscle neoplasm characterized by the presence of spindle cells with cigar-shaped nuclei, interlacing fascicles, and a whorled pattern. "Many proteins such as F3, WNT2, CDH1, and LIF shown in the protein–protein interaction networks are well known in leiomyoma pathogenesis, and others, such as ICAM1, CXCL8, CCL2, and NANOG are novel and require further investigation." (PMID 36835153, 2023).
cancer (223 papers, 1998 to 2026). A tumor composed of atypical neoplastic, often pleomorphic cells that invade other tissues. "Specifically, the F3 gene that encodes tissue factor (TF), a major factor involved in the pro-coagulant activity of cancer, was overexpressed approximately 4.5-fold in the VTE group vs. the control group (log2 fold change = 2.16, p < 0.0001)." (PMID 35326647, 2022). "F3 (tissue factor III) encodes a glycoprotein receptor for coagulation factor VII and initiates blood coagulation, but has also been implicated in cancer metastasis." (PMID 31217031, 2019). "The binding of F7 to tissue factor (F3) initiates the blood coagulation cascade and F3 plays a critical role in cancer development." (PMID 27409342, 2016).
tumor (223 papers, 1992 to 2026). "While a moderate correlation was found between VTE risk and expression of Tissue Factor (F3), a major pro‐coagulant factor, the authors noted heterogeneity across tumour types." (PMID 37147936, 2023). "For example, PN-, MES- and CL-type tumours markedly differ in the expression of F3/TF (tissue factor) gene encoding the central cell-associated, transmembrane receptor and regulator of the extrinsic coagulation cascade." (PMID 38188342, 2023). "Overexpression of the F3 gene has also been associated with cell migration/cytoskeletal reorganization and tumor progression." (PMID 32934781, 2020). "Indeed, great differences exist across different tumor types in the expression of F3 mRNA, which encodes the main activator of coagulation, the tissue factor (TF)." (PMID 36900323, 2023). "F3, encoding coagulation factor III, a high-affinity receptor that induce the activation of coagulation factor VII, thereby increasing VTE risk in various tumor types." (PMID 39179711, 2024). "The coagulation factor III (F3) was the gene with highest expression in LNCaP tumor xenograft as compared to cultured cells." (PMID 33808801, 2021). "F3 encodes coagulation factor III, a cell‐surface glycoprotein that can initiate blood coagulation cascades in the extrinsic coagulation pathway, and has also been reported to participate in tumor angiogenesis, but its association with radioresistance remains to be elucidated." (PMID 35505641, 2022).
infection (29 papers, 2012 to 2025). The state of being infected such as from the introduction of a foreign agent such as serum, vaccine, antigenic substance or organism. "Interestingly, the CD3+ T cell infiltrate was unable to recruit further macrophages, whereas in mice immunized with the rAsp f3-vaccine, T cell recruitment of macrophages to the point of infection appears to be associated with successful clearance of the fungal pathogen." (PMID 23024640, 2012).
F3 also shares sentences with these, for which no sentence is quoted: COVID-19 (64 papers); breast carcinoma (34); endothelial dysfunction (32); atherosclerosis (23); coagulopathy (17); ovarian carcinoma (16); pancreatic cancer (15); cervical cancer (13); diabetes (12); venous thromboembolism (12); Thromboembolism (11); Disseminated intravascular coagulation (10); viral infection (10); glioblastoma (9); Hyperglycemia (9); myocardial infarction (7); prostate carcinoma (7); Obesity (6); type 2 diabetes (6); acute respiratory distress syndrome (5); ischemic stroke (5); Stroke (5); systemic lupus erythematosus (5); colon cancer (4); haemophilia (4); hemophilia A (4); pneumonia (4); preeclampsia (4); Thrombocytosis (4); thrombotic disease (4).
A further 150 diseases each share a sentence with F3 in 3 papers or fewer.